SIRT3 (sirtuin 3)
Diseases named in the same sentence as SIRT3 in open-access papers (continued):
Sharing a sentence is not in itself a finding about the gene and the disease.
cancer (continued). "Contribution of SIRT3 in cancer genetics is discussed extensively in the following segment." (PMID 27686535, 2017). "In this mouse model, a proportion of SIRT3 KO mice develop spontaneous cancer at old age." (PMID 27352213, 2016). "Moreover, suppression of the Sirt3-mediated mitophagy promotes apoptotic cell death in the hypoxic cancer cells likely by enhancing the degradation of anti-apoptotic proteins Mcl-1 and survivin through a ROS-dependent proteasomal pathway." (PMID 27270321, 2016). "In this study, we therefore intend to pool and analyze clinical data reported from multiple research studies in order to provide a complete, exhaustive summary of current literatures relevant to the prognostic and clinicopathological roles of SIRT3 in various human cancers." (PMID 27483432, 2016). "In certain type of cancers, the participation of SIRT3 protein in hormonal regulation may be a potential contributing factor." (PMID 27483432, 2016). "However, correlation is found by subgroup analyses in a certain type of cancers, which indicates that the expression and function of SIRT3 are cancer type specific." (PMID 27483432, 2016). "The downregulation of SIRT3 and SIRT4 may lead to enhanced acetylation status and ROS generation in mitochondria, which are tightly associated with higher cancer risk." (PMID 26785117, 2016). "Our data suggest that controlling the activity of SIRT3 might be an alternative approach to manage c-MYC in cancer cells." (PMID 26317998, 2015). "In addition, SIRT3 silencing also promoted cancer cell growth as shown in the three dimensional soft agar model." (PMID 26317998, 2015). "To explore whether SIRT3 could inhibit Akt phosphorylation at Ser473 by blocking ROS, we used antioxidant N-acetyl cysteine (NAC) to suppress the high ROS level in SIRT3 knockdown cancer cells and measured the p-Akt(Ser473) level concurrently." (PMID 26317998, 2015). "Indeed, the ubiquitination level of c-MYC protein was increased in SIRT3 overexpressed cancer cells." (PMID 26317998, 2015). "SIRT3 was mainly expressed in the cytoplasm of cancer tissues." (PMID 25105144, 2014). "This work indicates that a decrease in SIRT3 may in fact be required for the metabolic reprogramming and the shift to glycolysis, which characterizes cancer cells." (PMID 24955214, 2014). "However, the expression status of Sirt3 in human HCC specimens is still ambiguous and the relationship between Sirt3 expression and cancer prognosis is still unclear." (PMID 24774224, 2014). "Although some investigators have suggested a particular role for SIRT3, these reports underscore the complexity of the biologic functions of SIRT3, which may differ according to the tissue of origin or cancer type." (PMID 23800187, 2013). "Accordingly, this suggests that SIRT3 may regulate the initiation and progression of cancer by controlling the cellular redox balance." (PMID 23800187, 2013). "The ability of CR to reduce oxidative stress was recently shown to be dependent on SIRT3, a deacetylase and mice deficient in SIRT3 were shown to be prone to both aging and cancer and failed to respond to CR." (PMID 22934068, 2012). "There is no previous study reporting the association between SIRT3 expression and prognosis in cancer." (PMID 23272146, 2012). "However, on subdividing the cancer biopsies by nodal status, SIRT3 expression, like that of SIRT7, was greater in node-positive breast cancer compared to normal breast tissue." (PMID 17003781, 2006).
cancer (continued). "Here we show that overexpression of arg-ii or elevated expression of arg-ii triggered by hypoxic conditions could both induce nuclear deformation through the decreased Sirt3/increased mtROS axis in both types of cancer cells as demonstrated in our current study." (PMID 40177131, 2025). "Integration of genomic data (e.g., SNPs in SIRT1, SIRT3, PGC‐1α), transcriptomic signatures (e.g., inflammatory and proliferative gene expression), and metabolomic profiles (e.g., NAD+/NADH ratio, redox metabolites) can identify individuals at high cancer risk." (PMID 40673471, 2025). "Importantly, the development of context-specific SIRT3 modulators may offer a promising strategy for personalized cancer therapies." (PMID 40860195, 2025). "Therefore, SIRT3 expression could be used to screen for people at the time of cancer diagnosis who are more likely to develop metastases or drug-resistant illness." (PMID 38816444, 2024). "Moreover, SIRT3 suppression led to homologous recombination repair inhibition and markedly sensitized cancer cells to IR and DNA-damaging chemicals, highlighting SIRT3 as a potential target for cancer therapy." (PMID 39002667, 2024). "In addition, the timing of cancer development in which SIRT3 is analyzed is also important." (PMID 38931477, 2024). "We investigated whether SIRT3 knockdown can sensitize cancer cells to IR." (PMID 39002667, 2024). "Furthermore, we propose that modulating cGAS and SIRT3 activities could be potential strategies for cancer therapy." (PMID 39002667, 2024). "In SIRT3-deficient cells, the heightened production of ROS enhances IRP1’s binding affinity to IREs, leading to the aberrant upregulation of iron-related genes such as the transferrin receptor (TfR1), which governs iron uptake and promotes cancer cell proliferation." (PMID 39682281, 2024). "Moreover, the expression level of SIRT3 can also be reduced by some compounds, thereby demonstrating the same effect as SIRT3 inhibitors, ultimately exerting antitumor activity and potentially offering therapeutic benefits for cancer treatment." (PMID 38773972, 2024). "Furthermore, the development of more specific SIRT3 activators would be desirable, as so far only less selective compounds with biological activity themselves have been tested, making it difficult to identify the exact role played by SIRT3 in the observed anti-cancer effects of these compounds." (PMID 37345199, 2023). "Therefore, to maintain appropriate Sirt3 level with NAD+ supplementation or physical exercise may be beneficial to cancer prevention during aging." (PMID 36739437, 2023). "Thus, it was rational to hypothesize that PROX1 interacts with transcriptional coregulators or epigenetic modifiers to regulate SIRT3 expression and thus modify cancer cell behavior." (PMID 36594098, 2023). "Interestingly, the dichotomous role of SIRT3 in cancer, which has emerged recently, might be explained by its dependency to mitochondrial NAD+ pool and thus to mitochondrial NAD+ “supplier” like the mitochondrial CI." (PMID 37533102, 2023). "However, the benefits of using SIRT3 positive modulators as adjuvants in cancer treatment seem clear, and many patients could benefit from them." (PMID 37345199, 2023). "However, the role of Sirt3 in cancer initiation and progression is still controversial." (PMID 36739437, 2023). "SIRT3 can promote oxidative phosphorylation and inhibit glycolysis in the regulation of mitochondrial metabolism, which may be one of the reasons why it plays a dual role in cancer." (PMID 35571098, 2022).
cancer (continued). "The depletion of SIRT3 in large B cell lymphoma blocks glutamine flux to the tricarboxylic acid (TCA) cycle through inhibition of glutamate dehydrogenase that results in the reduction of acetyl-CoA pools, which causes the induction of autophagy in cancer cells." (PMID 35897717, 2022). "Moreover, SIRT3 may play a dual role in cancer metastasis by affecting epithelial-to-mesenchymal transition (EMT)." (PMID 35832551, 2022). "Therefore, activation of SIRT3 protein may be a way to improve cancer treatment, especially to overcome the resistance of cancer cells to chemotherapy drugs." (PMID 35832551, 2022). "The specific connection between miRNA and SIRT3 role, and whether miRNA can be used as an indicator of SIRT3-mediated related cancer development process should be further explored, which provides a potential basis for targeting SIRT3 to find new approaches in cancer therapy." (PMID 35832551, 2022). "However, SIRT3 plays a carcinogenic role in some OXPHOS-addiction cancers, SIRT3 could promote glycolysis and tumorigenesis by maintaining ROS levels at an appropriate level, which depends on the cellular context." (PMID 35832551, 2022). "Similarly, the impact of SIRT3 on cancer chemoresistance is also bidirectional." (PMID 35832551, 2022). "Interestingly, SIRT3-mediated activation of MnSOD can promote EMT in cancer." (PMID 35832551, 2022). "Therefore, SIRT3 is a potential therapeutic target for the treatment of cancer." (PMID 35433629, 2022). "Thus, although further studies are required to establish its clinical potential, SIRT3 may represent an important factor for both cancer diagnosis and therapeutic development." (PMID 35671305, 2022). "Importantly, SIRT3 is a potentially attractive molecular target based on its dual role in cancer." (PMID 35832551, 2022). "New experimental designs may be pivotal to validate SIRT3 as a cancer regulator in CR." (PMID 34202278, 2021). "However, whether Sirt3 plays a role of oncogene or tumor suppressor in different cancer is still controversial." (PMID 34405009, 2021). "Therefore, SIRT3, like other SIRTs, is assumed to have a dual role in cancer cells." (PMID 33669567, 2021). "For instance, it cannot be ignored that the application of SIRT3 inhibitors in some OXPHOS-addiction cancers seems very promising, but in regarding to the protective effects of SIRT3 on various human organs, inhibition of SIRT3 might partially bring multiple organ toxicities." (PMID 32724473, 2020). "Moreover, the dual role SIRT3 plays in cancer development is intriguing." (PMID 32724473, 2020). "Thus, specific SIRT3 target proteins and the reactive species contributing to the progression of RILD, merit investigation to establish causal mechanisms for IR-induced chronic liver toxicity and develop strategies to prevent RILD in cancer survivors." (PMID 32403251, 2020). "However, in certain cancers, SIRT3 were significantly upregulated." (PMID 31113446, 2019). "Therefore, it deserves our further study on the effect and mechanism of SIRT3 in cancer." (PMID 28947845, 2017). "Therefore, modulation of SIRT3 activity could be an approach to improve therapies against cancer, especially to overcome acquired resistance to treatment." (PMID 28704962, 2017). "In addition, PSMD13 and SIRT3 share a promoter, and PSMD13, a proteasome subunit, is involved in the degradation of abnormal proteins, cellular senescence and ageing and variants in this gene have previously been associated with the onset of various cancers." (PMID 29064820, 2017). "Presumably, an overexpression of SIRT3 may help cancer cells divide and grow further." (PMID 27686535, 2017). "Interestingly, SIRT3 is known to be involved in both the cancer and ageing processes." (PMID 29064820, 2017). "Indeed, Sirt3 expression is decreased in many different human cancers." (PMID 27023612, 2016).
cancer (continued). "That SIRT3 may be involved in mediating a response to chemotherapy is interesting, given recent developments highlighting that fasting can protect normal/healthy cells from chemotherapy, while sensitising cancer cells to its effects." (PMID 26121130, 2015). "Thus, in addition to the well-documented SIRT3-mediated mitochondrial homeostasis in normal cells, SIRT3 may enhance glycolysis and cell proliferation in SIRT3-expressing cancer cells." (PMID 26121691, 2015). "Thus SIRT3-LDHA-mediated glycolysis metabolism may be a potential therapeutic target to treat cancer cells that express SIRT3." (PMID 26121691, 2015). "Thus, we speculate that Sirt3 might exert anti-apoptotic activity under various pathological conditions except for in cancer cells, which needs to be further investigated." (PMID 25196599, 2014). "In addition to suppressing the formation of cancer, SIRT3 can also combat established tumors." (PMID 23474711, 2013). "However, the exact mechanisms how SIRT3 is involved in cancer are largely unclear." (PMID 23230084, 2012). "SIRT3 could potentially be used to combat age-related decline and cancer." (PMID 21307404, 2011). "Furthermore, SIRT3 knockout mice have signs of accelerated aging and cancer." (PMID 21386135, 2011). "SIRT3 also influences autophagy, a process necessary for cellular maintenance and the recycling of cellular components, which is important in preventing diseases such as cancer (although in this case, it may act as a promoter or a suppressor) and neurodegenerative disorders." (PMID 40710366, 2025). "In DLBCL, SIRT3 activates glutamate dehydrogenase (GDH) thereby enhancing tricarboxylic acid (TCA) cycle metabolism and promoting cancer onset and development." (PMID 39215785, 2025). "Because SIRT3 (a mitochondrial deacetylase) plays critical roles in the regulation of ferroptosis in other cancers, such as GBM, we performed bioinformatic analysis using UALCAN to examine the relationship of the expression of SIRT3 and SLC25A22." (PMID 40298644, 2025). "This suggests that the SIRT3-CAVB axis is conserved among cell lines, although probably more robust in cancer cells that have evolved in an acidic microenvironment." (PMID 38931477, 2024). "Accordingly, we have summarized about 21 small-molecule compounds targeting SIRT3 and 3 small-molecule compounds targeting SIRT5 for the current cancer therapy." (PMID 38773972, 2024). "In PCa cells, the suppression of SIRT3 by the AR and its coregulator SRC-2 enhances ACO2 activity, promoting citrate synthesis and favoring aggressive cancer phenotypes." (PMID 39796040, 2024). "4-HNE increased the growth of cancer cells and upregulated the level of HIF-1α through the inhibition of Sirtuin-3 (SIRT3)." (PMID 38674143, 2024). "SIRT3 is also involved in various RCD pathways to exhibit distinct functions, depending on the cellular context and cancer type." (PMID 38773972, 2024). "Mitochondrial sirtuins, especially SIRT3, SIRT4, and SIRT5, emerge as key regulators of cancer metabolism." (PMID 38331199, 2024). "SIRT1 helps cancer cells survive chemotherapy, SIRT2 inhibits cell growth, and SIRT3 controls mitochondrial health, while SIRT4, SIRT5, SIRT6, and SIRT7 each influence metabolism, angiogenesis, and metastasis." (PMID 39682281, 2024). "On the other hand, SIRT3 inhibits the Wnt/β-catenin pathway and, indirectly, Twist1, Twist2, and Snail2, which are tightly connected with EMT progression, cancer invasion, and metastasis." (PMID 35745656, 2022). "Among mitochondrial sirtuins, SIRT3 has an important role in EMT regulation and metastatic motility in several cancer phenotypes." (PMID 35745656, 2022). "Herein, the anti-cancer effects of RES and cis-DDP combination were examined against the SiHa cell line, and an attempt was made to study the SIRT-3-related mechanism." (PMID 35865961, 2022).
cancer (continued). "In our study, SIRT3 silencing significantly compromised the growth inhibition in the RES + cis-DDP group, and it suggested that the anti-cancer effect of RES + cis-DDP was SIRT3-dependent." (PMID 35865961, 2022). "We envision that enhancement of SIRT3 activity and replenishment of NAD+ levels result in a multifaceted metabolic rewiring, which can oppose NF1-related cancer growth by affecting multiple bioenergetic pathways." (PMID 35393510, 2022). "Presented interactions between Sirt3 and MUTYH, NEIL1, and APE1 in cancer cells and the effect of Sirt3 on the cellular response to oxidative stress indicate the necessity of Sirt3 for proper cell antioxidative reaction." (PMID 35440893, 2022). "Moreover, down-regulation of SIRT3-mediated elevated ROS levels could promote the activation of the steroid receptor coactivator (Src)/focal adhesion kinase (FAK) signaling pathway to enhance cancer metastasis." (PMID 35832551, 2022). "We performed western blot to detected SIRT3-AMPK-mTOR-HIF-1α expression in NSCLC cells and cancer tissues." (PMID 33819917, 2021). "SIRT3, SIRT4, and SIRT5 were primarily mitochondrial proteins, which have emerged as critical regulators of diverse biological events, such as cancer progression." (PMID 33282964, 2020). "The resistance of cancer cells to A671 correlated with diminished SAP18 activation and sustained SIRT3 expression." (PMID 33273692, 2020). "Of which, SIRT3 represses ROS dependent Src/FAK signaling and promotes the proliferation, migration and metastasis of cancer cells." (PMID 32724473, 2020). "SIRT3 is the upstream deacetylase of PDC that deacetylates and activates PDC to inhibit glycolysis and promote apoptosis in cancer cells." (PMID 32724473, 2020). "SIRT3 controls the EMT process and metastatic motility of cancer cells through Twist in ovarian carcinoma." (PMID 31817470, 2019). "Sirtuin- (SIRT-3), phospho-mammalian target of rapamycin (p-mTOR) and hypoxia-inducible factor- (HIF-1α) are involved in metabolism and cancer." (PMID 30917505, 2019). "Sirtuin-3 (SIRT3) is a major mitochondrial NAD(+)-dependent deacetylase and plays a key role in the progression and development of human cancers." (PMID 27483432, 2016). "Therefore, in specific cancers or cellular events, the shuttling and interaction of SIRT3 with various substrates in different subcellular localization might be responsible for the dual role of SIRT3." (PMID 27483432, 2016). "Since SIRT3 was remarkably downregulated in HCC cell lines and cancer tissues, we next further examined its expression in 248 paraffin-embedded HCC tissues." (PMID 23272146, 2012). "Considering the important and interconnected role of glutamine, SIRT3 and SIRT5 for cancer growth and progression, our hypothesis is that a simultaneous modulation of SIRT3 and SIRT5 could represent a valid anti-tumoral strategy." (PMID 41599625, 2025). "Although previous research showed that SIRT3 and SLC25A22 had important roles in regulating ferroptosis in cancer cells, the present study is the first to identify a correlation and interaction of these two proteins in antagonizing the RSL3-induced ferroptosis of LUAD cells." (PMID 40298644, 2025). "Interestingly, the post-translational regulation of HSD17B4 stability through acetylation at lysine 669—modulated by sirtuin 3 (SIRT3) and CREB-binding protein (CREBBP) —provides a potential mechanism for fine-tuning HSD17B4 activity in the context of cancer." (PMID 40647540, 2025).